RNU6-637P (RNA, U6 small nuclear 637, pseudogene)
Gene: Small nuclear RNA gene on chromosome 3 (169,720,187 to 169,720,293, reverse strand). Ensembl gene ENSG00000206777.
Homologues: Orthologues: chimpanzee U6 (97% identical), rat U6 (93% identical), dog U6 (87% identical), pig U6 (87% identical), macaque U6 (79% identical). Paralogues in human: RNU6-12P (94% identical), RNU6-13P (94% identical), RNU6-25P (94% identical), RNU6-32P (94% identical), RNU6-41P (94% identical), RNU6-1 (93% identical), RNU6-17P (93% identical), RNU6-18P (93% identical), RNU6-19P (93% identical), RNU6-2 (93% identical), RNU6-33P (93% identical), RNU6-35P (93% identical), and 1287 more.